AR (androgen receptor)
Diseases named in the same sentence as AR in open-access papers (continued):
Sharing a sentence is not in itself a finding about the gene and the disease.
prostate carcinoma (continued). "SIRT1, for example, fosters chemoresistance and castration-resistant prostate cancer through metabolic reprogramming, immune modulation, androgen receptor signaling, and enhanced DNA repair." (PMID 39796040, 2024). "Androgen receptor axis-targeted therapies (ARATs) represent a paradigm shift in the management of prostate cancer." (PMID 39409956, 2024). "The biological analyses and antiproliferative activity of the synthesized compounds (3a–p) as potential candidates for prostate cancer therapy showed excellent anticancer properties against the tested AR+LNCaP and AR-PC-3 prostate cancer cell lines." (PMID 39062524, 2024). "Using AR‐positive prostate cancer cell lines, we showed that MA inhibited AR expression in LNCaP and 22Rv1 cell lines, including AR‐regulated proteins prostate‐specific antigen (PSA) and human kallikrein 2 (hK2), and the AR‐V7 variant in 22Rv1 cells." (PMID 38605607, 2024). "This includes critical roles in CRC regulation for TFs such as MYOD in rhabdomyosarcoma, AR in prostate cancer, and IRF8 in AML." (PMID 39536500, 2024). "Their mechanistic study on nano-Se confirmed that it inhibits the growth of prostate cancer cells through AR suppression, which is necessary for both androgen-dependent and independent prostate cancers." (PMID 38398553, 2024). "A promising approach to combat aggressive prostate cancer involves androgen receptor degraders, which break down the crucial protein driving cancer progression." (PMID 38339414, 2024). "Androgen deprivation therapy, aiming to suppress androgen receptor signaling, remains the preferred method in prostate cancer treatment." (PMID 38921890, 2024). "Critically, AR signaling has been shown to be interconnected with DNA-damage and with DNA-repair genes in prostate cancer cells and tumor models." (PMID 38956684, 2024). "LLPS of androgen receptor (AR) also plays a significant role in the mechanism of anti-androgen resistance in prostate cancer." (PMID 39253293, 2024). "Androgens from the testis and the adrenal gland bind to androgen receptor (AR) to activate AR signaling and facilitate prostate cancer progression." (PMID 39146021, 2024). "This review highlights the critical roles of the AHR and AR signaling pathways in the aggressive nature of prostate cancer within AA populations." (PMID 39600743, 2024). "The compound has also demonstrated efficacy in prostate cancer by targeting androgen receptor signaling and in head and neck cancers through the inhibition of tumor growth and angiogenesis." (PMID 39061221, 2024). "In advanced prostate cancer (PC), persistent activity of the androgen receptor (AR) is a key driver of tumor progression, patient survival, and metastases." (PMID 39207857, 2024). "In fact, previous studies have demonstrated that MYSM1 interplays with p/CAF to form a co-regulatory protein complex that stepwise synergizes histone ubiquitination and acetylation for AR-dependent gene activation in prostate cancer cells." (PMID 38177530, 2024). "Abnormal transcription activities driven by SEs, such as cyclin dependent kinase 7 (CDK7), bromodomain and extra-terminal domain (BET)/bromodomain containing 4 (BRD4), and androgen receptor (AR), have been reported to influence prostate cancer phenotypes." (PMID 38410974, 2024). "Carbidopa, an AhR antagonist, has been shown to promote the ubiquitination and proteasomal degradation of AR, leading to a significant reduction in AR protein levels and decreased prostate cancer cell viability." (PMID 39184676, 2024). "The expression of CBX1 is elevated in prostate cancer and directly promotes the binding of the AR to the ARE." (PMID 39598420, 2024). "These concentrations of DHT are comparable to those measured in recurrent prostate cancer and are at levels that can transactivate the AR." (PMID 38339092, 2024).
prostate carcinoma (continued). "What this shows is the role played by CHK2 in Androgen Receptor regulation, linking DNA damage repair with prostate cancer growth and proliferation through Androgen Receptor mediation." (PMID 39410867, 2024). "In this way, it brings together AR, the key driver of prostate cancer, and MDM2 (mouse double minute 2 gene), an E3 ubiquitin ligase leading to ubiquitination and subsequent degradation of f-AR and AR-V7 in prostate cancer cells." (PMID 39598525, 2024). "Activation of the P13K/Akt/mTOR pathway has been reported to occur in approximately half of advanced prostate carcinoma with significant cross-talk between P13K/Akt/mTOR and AR signaling." (PMID 39273701, 2024). "Among all cancer types, androgen receptor (AR) is most highly expressed in breast cancer after prostate cancer (The Human Protein Atlas.org." (PMID 38349455, 2024). "AR has long been studied in prostate cancer, as it was found to be a key driver for prostate cancer development and progression." (PMID 39768587, 2024). "The high global mortality burden of prostate cancer, despite medical treatments such as androgen deprivation or AR antagonist therapy, highlights the need to explore alternative strategies." (PMID 38958553, 2024). "A phosphorylated isoform of hnRNP K is localized in the NM of prostate cancer, and the hyperphosphorylation of hnRNP K co-localized with AR in the NM and exerted AR co-activator functions." (PMID 39000020, 2024). "The PI3K/Akt and AR pathways are critical modulators of the development and progression of prostate cancer by mediating the transcription of target genes that regulate the growth and differentiation of prostate epithelial cells." (PMID 38254705, 2024). "AR inhibitors are applied for the treatment of prostate cancer, but drug resistance is a major clinical problem." (PMID 39627201, 2024). "Yang and group studied the interaction and crosstalk between the AR and Wnt/β-catenin signaling in prostate cancer." (PMID 38372868, 2024). "We herein investigated the functional role of LPHNs in the growth of prostate cancer, in relation to AR signaling, primarily via their activation (e.g., ligand treatment) and inactivation (e.g., knockdown) in cell line models." (PMID 39000396, 2024). "Particularly in cancer-associated fibroblasts, the transcriptional factor androgen receptor (AR) binds to FLNACT, mediates nuclear translocation of AR, and subsequently increases incidence of prostate cancer." (PMID 39195282, 2024). "Androgen receptor signalling reportedly promotes the PPP through mTOR-mediated up-regulation of G6PD in prostate cancer." (PMID 39025830, 2024). "Marine compounds, sintokamide A (SINT1) and rhizochalinin (Rhiz) showed anti‐prostate cancer effects by targeting AR." (PMID 38605607, 2024). "The combination of shorter CAG repeats and higher baseline AR activity contributes to the aggressive progression of prostate cancer in AAs, resulting in increased resistance to ADT." (PMID 39600743, 2024). "Previous research has shown that PAM can specifically elevate ROS levels in androgen receptor (AR)-independent prostate cancer cells, which in turn suppresses cell migration, triggers G0/G1 phase cell cycle arrest and promotes apoptosis." (PMID 39769029, 2024). "The androgen receptor (AR) is an attractive target for treating prostate cancer, considering its role in the development and progression of localized and metastatic prostate cancer." (PMID 38958553, 2024). "Prostate cancer grows in an androgen receptor signaling-dependent manner and can be effectively treated by androgen deprivation therapy (ADT)." (PMID 39201655, 2024). "The androgen receptor (AR) is a key transcription factor that drives prostate cancer growth in response to androgenic hormones and is a regulator in castration-resistant prostate cancer (CRPC)." (PMID 39201018, 2024).
prostate carcinoma (continued). "PR has been shown to enhance motility and invasiveness in breast cancer, while AR activation by androgens is crucial for the initiation and progression of prostate cancers." (PMID 39327610, 2024). "It effectively targets the tumor microenvironment (TME) and androgen receptor (AR) in prostate cancer, inducing growth inhibition, cell cycle arrest, apoptosis, and metastasis suppression." (PMID 39199550, 2024). "To further delineate these two possibilities, we examined publicly available AR ChIP-seq data in a prostate cancer cell line." (PMID 38575753, 2024). "Compounds 16–18 showed cytotoxicity against the prostate cancer cell line 22Rv1 (androgen receptor positive), with IC50 values of 13.9, 13.0, and 13.6 μM, respectively." (PMID 39852509, 2024). "Althoughthe azolato-bridged complexes also exert anticancer activity via a mechanism that is similar to that of current Pt-drugs,they also appear to interact with AR, which is a crucial moleculefor the proliferation of prostate cancer cells." (PMID 39258898, 2024). "It is important to note that the interpretation of these data is based on comprehensive studies of the AR cistrome in prostate cancer." (PMID 38338965, 2024). "Inducing ferroptosis in combination with ER or AR antagonists significantly inhibits the growth of ER-positive breast cancer or AR-positive prostate cancer, offering a novel therapeutic approach for cancers with specific genetic backgrounds." (PMID 39021564, 2024). "The upper and lower limits were achieved for the nuclear androgen receptor (NR-AR), a crucial transcriptional regulator and therapeutic target in prostate cancer." (PMID 38216614, 2024). "Enzalutamide (MDV3100) treatment also enhances CREB activation in AR-positive prostate cancer cells." (PMID 38233872, 2024). "Its main function is related to the proliferation of prostate cancers promoted by androgen receptor and IRE1-ɑ." (PMID 38303702, 2024). "Next, the correlation between androgen receptor expression and the combination of adiponectin and leptin levels was examined by immunostaining of prostate cancer tissue." (PMID 39201655, 2024). "Enzalutamide is an AR inhibitor that prolongs the survival of patients with advanced prostate cancer." (PMID 39253786, 2024). "During enzalutamide treatment of AR-positive prostate cancer cells, activated GR induces the expression of MYCN, which subsequently promotes NE differentiation." (PMID 39027480, 2024). "Despite extensive therapeutic targeting of the androgen receptor (AR), advanced prostate cancer commonly remains dependent on AR signaling." (PMID 38167882, 2024). "An androgen-response element (ARE) was identified upstream of exon 1 from LNCaP human prostate cancer cells and ligand-bound androgen receptor (AR) was shown to upregulate sGCα1 transcription." (PMID 39337539, 2024). "Activation of both SRs in prostate cancer cells, with endogenous AR and exogenous GR expression, was found to modulate the transcriptional activity of the other receptor." (PMID 39027480, 2024). "Using online CCLE data curated by the Broad Institute via a waterfall plot based on median expression, we found that AR has been noted to be more highly expressed in OS than in any other malignancies, including prostate cancer." (PMID 38361046, 2024). "In this study, we have identified the importance of ROR1 as a driver of cancer aggression in ARneg-AI prostate cancer, which is a form of prostate cancer that exhibits castration resistance and lacks a targetable AR." (PMID 39000112, 2024). "The androgen receptor (AR) is a key target in prostate cancer, and many current therapies for metastatic castration-resistant prostate cancer (mCRPC) target AR signaling." (PMID 39219215, 2024). "The use of androgen receptor (AR) inhibitors in prostate cancer gives rise to increased cellular lineage plasticity resulting in resistance to AR-targeted therapies." (PMID 38554106, 2024).
prostate carcinoma (continued). "Preclinical evidence suggests interplay between the androgen receptor, which largely drives the growth of prostate cancer cells, and PARP, providing a rationale for their co-inhibition." (PMID 38049622, 2024). "This study explores the association of two gene polymorphisms (AR (CAG)n and APEX1 c.444T>G (p.Asp148Glu)) with biochemical recurrence in Argentinian patients with prostate cancer." (PMID 39594771, 2024). "Our previous data also demonstrated that AR upregulated the expression of NCAPD3 in prostate cancer." (PMID 38561330, 2024). "Androgen receptor (AR) transcriptional activity significantly influences prostate cancer (PCa) progression." (PMID 38275816, 2024). "PCA3 modulates prostate cancer (PCa) cell survival through modulating androgen receptor (AR) signaling." (PMID 38792557, 2024). "We identified miR-1271–5p as an androgen receptor modulatory microRNA and we show it can promote hormone sensitive prostate cancer cell growth." (PMID 39267821, 2024). "In prostate cancer, the reactivation of the androgen receptor represses the Smad3 gene promoter activity." (PMID 38675493, 2024). "Prostate cancer cell proliferation and survival are driven by AR, and tumors initially respond to androgen-deprivation therapy (ADT)." (PMID 38410785, 2024). "Testosterone plays a significant role in the development and progression of prostate cancer as it stimulates the growth of cancer cells through androgen receptor activation." (PMID 39830537, 2024). "By gaining a deeper understanding of the roles of AHR and AR signaling in prostate cancer, particularly in the context of ethnic diversity, we aim to work toward reducing these disparities and improving outcomes for all patients." (PMID 39600743, 2024). "Increased levels of both total and K421-acetylated KDM3A have been reported in prostate cancer cells resistant to the AR antagonist enzalutamide." (PMID 39394462, 2024). "The androgen receptor (AR) and its signaling pathways play central roles in the proliferation, migration, invasion, and differentiation of prostate cancer cells." (PMID 39588149, 2024). "Contrary to our results, in prostate cancer, miR-320 was demonstrated to be repressed epigenetically and upon activation to suppress androgen receptor expression by targeting its translation, thereby inhibiting prostate cancer cell growth." (PMID 38666942, 2024). "In this study, we investigated how MED12 and CDK8/19 influence cancer-driven processes in prostate cancer cell lines, focusing on AR activity and the enzalutamide response." (PMID 39253786, 2024). "Studies have shown that GR expression increases in some prostate cancer cells following treatment with AR inhibitors, enabling these cells to bypass AR blockade and continue to grow." (PMID 39184676, 2024). "Androgen deprivation therapies (ADT) focusing on the androgen receptor (AR) remain the cornerstone treatments for prostate cancer (PCa)." (PMID 38777812, 2024). "Prostate cancer (PCa) cells rely on androgen receptor (AR) signaling, and therapies targeting this pathway can inadvertently activate compensatory mechanisms like mTOR." (PMID 39796704, 2024). "This interaction results in TRIM24 accumulation and AR signaling activation, thereby promoting the tumorigenesis of prostate cancer." (PMID 39160596, 2024). "The persistence of AR signaling in prostate cancer cells, even after androgen deprivation therapy (ADT), is a significant challenge in managing the disease." (PMID 39600743, 2024). "We have investigated the roles of different steroid hormone receptors in controlling AR expression using prostate cancer cell models, with a focus on known genomic loci." (PMID 39088439, 2024). "As AR is involved in the growth of prostate cancer cells, these interactions imply the potential to inhibit the growth of prostate cancer cells." (PMID 38699722, 2024).
prostate carcinoma (continued). "Here, we aimed to analyze the transcriptomic response of prostate cancer cells to irradiation by photons in comparison to carbon ions, focusing on DNA damage, DNA repair and androgen receptor signaling." (PMID 38956684, 2024). "In prostate cancer, when AR is stimulated, it is recruited to super enhancers, where it forms liquid condensates." (PMID 38658705, 2024). "Another significant mechanism is NED, where prostate cancer cells lose their dependence on AR signaling and gain characteristics of neuroendocrine cells." (PMID 39184676, 2024). "TRIM24 not only fosters prostate cancer growth but also sensitizes cells to low androgen levels by binding to gene promoters and activating pathways involved in both cell proliferation and AR signaling." (PMID 39160596, 2024). "Androgen deprivation therapy (ADT) targeting androgen/androgen receptor (AR)- signaling pathways is the main therapy for advanced prostate cancer (PCa)." (PMID 38336745, 2024). "AU-1530 suppressed tumor growth in xenograft models of prostate cancer and synergized with the AR antagonist, enzalutamide." (PMID 38390898, 2024). "Noteworthily, the authors also found hyperactive AR-driven, androgen-independent sGCα1 expression that correlated with prostate cancer proliferation." (PMID 39337539, 2024). "Understanding the intricate interactions between androgen receptor signalling, paracrine factors, and apoptosis regulation is essential for developing effective treatments for advanced prostate cancer." (PMID 39554609, 2024). "CCS1477 exhibited potent growth inhibition of the AR-positive prostate cancer cell lines VCaP, 22Rv1 and LNCaP95 with IC50 values below 100 nM." (PMID 39407454, 2024). "We detected that the replacement of AR by GR in enzalutamide-exposed prostate cancer cells occurs almost exclusively at pre-accessible chromatin sites displaying FOXA1 occupancy." (PMID 38015476, 2024). "One significant aspect of prostate cancer is the androgen receptor (AR) signaling pathway which is exploited as a drug target by pharmacologic androgen deprivation or antagonistic AR blockade therapy in certain tumor stages." (PMID 38956684, 2024). "For example, mutant androgen receptor variants 7 and 9 have been detected as circulating plasma EVRNA tumor biomarkers in prostate cancer patients." (PMID 39062561, 2024). "Although PSA is consistently expressed in prostate cancer, its level of expression on a per-cell basis is lower than in normal prostate epithelium reflecting AR transcriptional activity." (PMID 39459070, 2024). "Ongoing research on the molecular underpinnings of AR function and resistance is crucial for developing more effective treatments, ultimately aiming to transform prostate cancer into a manageable chronic condition." (PMID 39335158, 2024). "Like reducing translocation of the androgen receptor (AR) from the cell surface to the nucleus in castration-resistant prostate cancer cells, and impeding transport of DNA-damage and repair components." (PMID 38433242, 2024). "AA men tend to express higher levels of AR in prostate cancer tissues, which contributes to the more aggressive nature of the disease in this population." (PMID 39600743, 2024). "For example, some ligand-independent members of nuclear receptor superfamily-designated as orphan nuclear receptors play significant roles in the growth regulation of prostate cancer via multiple AR-dependent or -independent pathways or mechanisms." (PMID 38530778, 2024). "Prostate cancer can synthesize androgens intratumorally, maintaining AR signaling despite castrate serum testosterone levels." (PMID 39335158, 2024). "In prostate cancer cells, xenografts, and clinical tumors, the direct activation of androgen receptor (AR)-mediated fatty acid elongase of very-long-chain fatty acid 5 (ELOVL5) has been shown." (PMID 39126035, 2024). "Androgen receptor (AR)-mediated transcription plays a critical role in normal prostate development and prostate cancer growth." (PMID 38352568, 2024).